ADRA1A (adrenoceptor alpha 1A)
Diseases named in the same sentence as ADRA1A in open-access papers (continued):
Sharing a sentence is not in itself a finding about the gene and the disease.
Dyskinesia (1 paper, 2023). A movement disorder which consists of effects including diminished voluntary movements and the presence of involuntary movements. "A variety of ADRs belonging to movement disorders (e.g., extrapyramidal disorder, Parkinsonism, and dyskinesia) were associated with several targets, including OPRK1 (9 drugs), CHRM2 (8 drugs), and ADRA1A (5 drugs)." (PMID 37468498, 2023).
edema (1 paper, 2020). An abnormal accumulation of fluid beneath the skin, or in one or more cavities of the body. "Variants for ADRA1A (rs2229126, TA) were only identified in individuals with pulmonary edema in the heterozygous state, which implies that life-threatening toxicity could occur following ritodrine use in homozygous ADRA1A variant carriers." (PMID 33166306, 2020).
glioma (1 paper, 2025). A benign or malignant brain and spinal cord tumor that arises from glial cells (astrocytes, oligodendrocytes, ependymal cells). "The top 5 main targets of semen strychni for the therapy of glioma were ADRB1, ADRB2, CHRM3, ADRA1A, and ESR1, based on the degree value of the software’s network function analysis." (PMID 41430985, 2025). "Stigmasterol, (S)-stylopine, isobrucine, icaride A, and isostrychnine N-oxide (I), which may act on key targets such as ADRB1, ADRB2, CHRM3, ADRA1A, and ESR1, are the main ingredients of semen strychni used to treat gliomas." (PMID 41430985, 2025). "The core components of semen strychni used in the treatment of glioma included stigmasterol, (S)-stylopine, isobrucine, icaride A, and isostrychnine N-oxide (I), which may operate on core targets such as ADRB1, ADRB2, CHRM3, ADRA1A, and ESR1." (PMID 41430985, 2025).
liver cancer (1 paper, 2022). An epithelial or non-epithelial malignant neoplasm that arises from the liver. "ADRA1A hypermethylation contributed to liver cancer initiation and was associated with patient prognosis as a promising biomarker for diagnosis." (PMID 36054420, 2022).
metabolic syndrome X (1 paper, 2022). "For example, in the subnetwork for metabolic syndrome X, pathogenesis genes AGTR2 and ADRA1A are at the top hierarchical layer for chemokine signaling, while IRF1, MXZB1, MTTP, and CNTC are at the top layer in cytokine signaling." (PMID 35404985, 2022).
Parkinsonism (1 paper, 2023). Characteristic neurologic anomaly resulting from degeneration of dopamine-generating cells in the substantia nigra, a region of the midbrain, characterized clinically by shaking, rigidity, slowness of movement and difficulty with walking and gait. "Rotigotine, a dopamine agonist used for Parkinson’s disease, was found to be an ADRA1A (α1a) agonist (AC50 = 3.3 nM); it has been described as an α2b agonist in a journal not curated by the sources used in our analysis." (PMID 37468498, 2023).
pterygium (1 paper, 2025). A wedge-shaped fibrovascular lesion arising from the bulbar conjunctiva and extending to the cornea. "The increased expression of TH, ADRA1A, ADRA1B, and ADRB2 suggests the involvement of the sympathetic system in the pathogenesis of pterygium." (PMID 40806545, 2025).
pulmonary edema (1 paper, 2020). Accumulation of fluid in the lung tissues causing disturbance of the gas exchange that may lead to respiratory failure. "In silico analysis of deleterious variants was performed, producing two putative East Asian population-specific variants, rs2229291 (CPT2) and rs2229126 (ADRA1A), located in genes with roles compatible with tocolytic-associated pulmonary edema." (PMID 33166306, 2020). "In the current study, we demonstrated that two variants in CPT2 and ADRA1A were selected as candidate variants for pulmonary edema." (PMID 33166306, 2020). "In the current study, we identified two final candidate variants in CPT2 and ADRA1A associated with ritodrine-induced pulmonary edema." (PMID 33166306, 2020). "Finally, the two final candidate variants located in CPT2 and ADRA1A were selected to be responsible for ritodrine-induced pulmonary edema." (PMID 33166306, 2020).
rectal adenocarcinoma (1 paper, 2024). "However, upon further differential gene expression comparative analysis, it was noted that although all genes except OPRM1 and ADRA1A showed expression in colon and rectal adenocarcinoma, their levels of expression were not as high as CTSB and CPNE1, which demonstrated the maximum expression." (PMID 38544823, 2024).
rectal cancer (1 paper, 2014). A primary or metastatic malignant neoplasm that affects the rectum. "Notably, many of these genes (ADRA1A, BARHL2, ERAS, ESRRG, RNF220 and ST6GALNAC5) are also targets of the Polycomb Repressor Complex-2, further supporting an important role of epigenetic crosstalk in controlling rectal cancer therapeutic responsiveness." (PMID 25261372, 2014).
steatosis (1 paper, 2024). Increased lipid within the cytoplasm of cells. "The use of ADRA1a antagonists can block SNS, enhance hepatic progenitor cell accumulation, and alleviate hepatic necrosis and steatosis." (PMID 39409181, 2024).
Vasovagal syncope (1 paper, 2019). A vasovagal episode or vasovagal syncope is the most common form of reflex syncope. "Our results suggest that the ADRA1A variant associates with positive tilt tests, but not with vasovagal syncope." (PMID 31850372, 2019). "The alpha adrenergic 1 receptor ADRA1A 1039T>C variant is involved in sympathetic transduction, and the Arg/Arg genotype of ADRA1A 1039 T>C significantly associated with positive tilt tests when comparing vasovagal syncope patients to asymptomatic controls with negative tilt tests." (PMID 31850372, 2019).
tumor (10 papers, 2008 to 2025). "The common prognostic genes between AS event and genes included KRT222, LENG8, APOB, SLC3A1, SCD5, AQP1, and ADRA1A, which played roles in tumor biology." (PMID 31140607, 2019). "The CXCR2 and ADRA1A closely interacted, and the signaling network of related genes indicated that the function module might involve in the immune response regulation in the tumor microenvironment." (PMID 36611170, 2023). "Among these genes, six (HOXA6, STC2, HSD17B8, TFAP2A, CYP1B1, and HOXC8) were reported to be osteogenesis-/chondrogenesis-related genes, and five (ADRA1A, TSPYL5, TES, TNFRSF10D, and MBP) were reported to be tumor-suppressor genes." (PMID 31889115, 2019). "ADRA1A and ZNF366 have proliferation regulatory functions that limit tumor cells from forming tumors/metastases in response to stimulators." (PMID 27136531, 2016). "Intriguingly, whether in HCC or ICC, many genes (such as ADRA1A and KIF4A) displayed some opposite features of AS events in tumor and normal tissues." (PMID 34760694, 2021).
cancer (4 papers, 2022 to 2024). A tumor composed of atypical neoplastic, often pleomorphic cells that invade other tissues. "ADRA1A in total appears to be the most engaged MMR during cancer, consistently downregulated." (PMID 39766077, 2024). "The ADRA1B gene is a member of the adrenergic receptor alpha 1 (ADRA1) subfamily, which also includes ADRA1A and ADRA1D, and has been shown to promote the development of cancer in the epinephrine cell pathway." (PMID 35372518, 2022).
psychiatric disorder (3 papers, 2020 to 2025). A disorder characterized by behavioral and/or psychological abnormalities, often accompanied by physical symptoms. "Of the 52 male-biased drug-adverse event pairs with SBAE-associated drugs with ADRA1A as a drug target, 20 male-biased adverse events were related to psychiatric disorders." (PMID 38167211, 2024). "In contrast, only one of the 126 female-biased ADRA1A adverse events was a psychiatric disorder." (PMID 38167211, 2024).
cardiac disease (1 paper, 2023). "The effects of selective Adra1a antagonists on cardiac disease with RAS hyperactivity have yet to be reported." (PMID 36736425, 2023).
kidney disease (1 paper, 2023). "Furthermore, ADRA1A affects renal functions via regulating Na+ reabsorption, renin secretion, renal blood flow and glomerular filtration rate, of which alterations cause kidney disease." (PMID 36134646, 2023).
ADRA1A also shares sentences with these, for which no sentence is quoted: schizophrenia (4 papers); diabetes (2); infection (2); insomnia (2); anxiety disorder (1); benign prostatic hyperplasia (1); Brugada syndrome (1); cardiovascular disease (1); colorectal cancer (1); dilatation (1); dilated cardiomyopathy (1); dry mouth (1); gastric carcinoma (1); Insulin resistance (1); movement disorder (1); Myocardial fibrosis (1); oligodendroglioma (1); phobia (1); Syncope (1); Synthesis (1); Urinary incontinence (1); uterine cancer (1); ventricular dilatation (1).